PSAP (prosaposin)
Diseases named in the same sentence as PSAP in open-access papers (continued):
Sharing a sentence is not in itself a finding about the gene and the disease.
mesothelioma (1 paper, 2022). A usually malignant and aggressive neoplasm of the mesothelium which is often associated with exposure to asbestos. "Pleural effusions from mesothelioma patients had significantly higher levels of prosaposin and SULF-1 than those from non-malignant disease patients." (PMID 36359323, 2022). "In conclusion, prosaposin and SULF-1 levels determined in pleural effusion may be promising biomarkers for differential diagnosis between mesothelioma and non-malignant pleural disease." (PMID 36359323, 2022).
neuroendocrine tumor (1 paper, 2025). "Potential for confusion with prostate cancer PSAP expression in a primary presacral neuroendocrine tumor." (PMID 40668272, 2025).
preeclampsia (1 paper, 2022). Preeclampsia is a hypertensive disorder of pregnancy that is characterized by new-onset hypertension with proteinuria presenting after 20 weeks of gestation, and depending on mild or severe forms may initially present with severe headache, visual disturbances, and hyperreflexia. "Posttranscriptional regulation of placental PSAP has also been implicated in early-onset preeclampsia." (PMID 35860693, 2022).
progressive supranuclear palsy (1 paper, 2025). A rare late-onset neurodegenerative disease characterized by supranuclear gaze palsy, postural instability, progressive rigidity, and mild dementia. "DB16954 (Ezeprogind) is a small molecule drug developed to treat Progressive Supranuclear Palsy (PSP), a tauopathy-related neurodegenerative disorder, by targeting the Progranulin– Prosaposin (PGRN–PSAP) axis and enhancing lysosomal function." (PMID 41256885, 2025).
Prosaposin deficiency (1 paper, 2009). "Prosaposin deficiency (pSap-d) and saposin B deficiency (SapB-d) are both lipid storage disorders caused by mutations in the PSAP gene that codes for the 65–70 kDa prosaposin protein, which is the precursor for four sphingolipid activator proteins, saposins A–D." (PMID 19267410, 2009).
prostate tumors (1 paper, 2013).
respiratory failure (1 paper, 2024). The significant impairment of gas exchange within the lungs resulting in hypoxia, hypercarbia, or both, to the extent that organ tissue perfusion is severely compromised. "However, we found the predicted effect of prosaposin on respiratory failure." (PMID 39049003, 2024).
rheumatoid arthritis (1 paper, 2025). A chronic, systemic autoimmune disorder characterized by inflammation in the synovial membranes and articular surfaces. "Both PSAP and CTSS were investigated if their expression in monocyte were changed by clinical conditions among 78 patients with rheumatoid arthritis in the dataset." (PMID 40581066, 2025).
silicosis (1 paper, 2020). Silicosis is a respiratory disease caused by breathing in (inhaling) silica dust. "Downregulation of PSAP might be contribute to silicosis therapy." (PMID 33119648, 2020).
skin cutaneous melanoma (1 paper, 2024). "Interestingly, we observed that despite the strong association of Galectin-1 (LGALS1) and PSAP with the stromal compartment, cancer cells appear to be the main source expressing these genes in skin cutaneous melanoma." (PMID 38384845, 2024).
small cell carcinoma (1 paper, 2011). A neuroendocrine carcinoma composed of small malignant cells which are often said to resemble "oat cells" under the microscope. "A comprehensive immunohistochemical panel to differentiate small cell carcinoma from poorly differentiated adenocarcinoma includes PSA, PSAP, P501s, and neuroendocrine markers, CD 56 being the most sensitive for small cell carcinoma." (PMID 22110988, 2011). "Immunohistochemistry can be helpful in distinguishing them, as small cell carcinomas can be positive (even focally) for at least one prostatic marker (PSA, PSMA, PSAP, or P501s) which are not expressed in lung tumors." (PMID 22110988, 2011). "Most small cell carcinomas are negative for the prostate markers (PSA, PSAP, and P501S), with some rare cases showing focal positivity, while poorly differentiated adenocarcinomas are usually diffusely positive for the same antibodies." (PMID 22110988, 2011).
Stroke (1 paper, 2022). Sudden impairment of blood flow to a part of the brain due to occlusion or rupture of an artery to the brain. "A recent study highlighting the role of GPR37 in mediating glial cell responses following stroke examined prosaposin levels within the peri-infarct region of wild-type and GPR37 knock-out (Gpr37-/-) mice and did not observe detectable differences in prosaposin expression." (PMID 35409385, 2022).
systemic lupus erythematosus (1 paper, 2025). An autoimmune multi-organ disease typically associated with vasculopathy and autoantibody production. "Existing research provides some support: PSAP reduces the proportion of CD8+ T cells in PBMC, and hydroxychloroquine (HCQ), an immunomodulatory drug used for RA and systemic lupus erythematosus (SLE), binds to saposin B (a cleavage product of PSAP)." (PMID 40696268, 2025).
Tinnitus (1 paper, 2022). Tinnitus is an auditory perception that can be described as the experience of sound, in the ear or in the head, in the absence of external acoustic stimulation. "Gene-based testing of SNPs summary statistic data identified PSAP and TNRC6 were significantly associated with tinnitus." (PMID 36581688, 2022). "The gene-based test identified PSAP was associated with tinnitus and tinnitus-related distress, and TNRC6 was associated with tinnitus." (PMID 36581688, 2022). "The genomic loci involving PSAP and TNRC6B showed suggestive association with tinnitus." (PMID 36581688, 2022).
unstable angina (1 paper, 2018). "The serum UA levels in patients with stable angina were significantly lower than those in patients with unstable angina and MI (one-way ANOVA, PSAP vs.MI < 0.05, and PSAP vs.UAP < 0.05)." (PMID 30425752, 2018).
Vestibular schwannoma (1 paper, 2025). A vestibular schwannoma (also known as acoustic neuroma, acoustic neurinoma, or acoustic neurilemoma) is a benign, usually slow-growing tumor that develops from the VIIIth cranial nerve supplying the inner ear. "Our cell communication analysis based on the curated receptor-ligand pair database showed that fibroblast in vestibular schwannoma microenvironment mainly regulated the biological behavior of tumor cells through PSAP/GPR37L1, MDK/(ITGA6 + ITGB1), IGF2/(ITGA6 + ) and MDK/LRP1 signaling axes." (PMID 40629113, 2025).
tumor (40 papers, 2013 to 2026). "PSAP, a secreted glycoprotein, has been associated with tumor progression and neuroimmune communication in various cancers." (PMID 41281377, 2025). "PSAP produces prosaposin, whose amplification is reported to cause carcinogenesis or tumor progression." (PMID 32762727, 2020). "PSAP is a purported AR activator associated with metastatic potential in a number of neoplasms." (PMID 26341737, 2015). "Collectively, these findings define a novel PSAP–TGFβ1–Sortilin axis that mediates SCs–tumor crosstalk and sustains PNI in GC." (PMID 41580724, 2026). "This pathway amplifies PSAP production and reinforces tumor–nerve interactions, establishing a feedforward paracrine loop that drives PNI." (PMID 41580724, 2026). "This indicates that PrSt/MSF-derived PSAP/Sap C stimulates PSAP transcription within tumor cells through paracrine signaling, possibly by enhancing AR activity, which forms a feed forward loop involving PSAP/Sap C and AR signaling in PCa cells." (PMID 40801564, 2025). "Mechanistically, prosaposin secreted by tumor cells activates pro-metastatic, bone marrow-derived MDSCs to secrete THBS1, fostering the creation of a metastasis-refractory environment in distant organs." (PMID 39930476, 2025). "In high-grade plasmacytoid ovarian cancer, the tumor microenvironment suppresses PSAP expression during progression, reducing secretion of anti-tumor protein thrombospondin-1 (TSP-1) and enabling immune evasion." (PMID 40801564, 2025). "The role of PSAP in cancers is complex, because it promotes or inhibits tumor growth depending on the context and it serves as a potential biomarker for various malignancies." (PMID 40801564, 2025). "High PSAP expression correlated with advanced tumor stage and reduced overall survival, indicating poorer prognosis." (PMID 40801564, 2025). "In stark contrast, contradictory findings of significantly lower PSAP levels have been observed in GBM plasma EVs relative to non-tumour controls." (PMID 38212481, 2024). "Immunohistochemically, PSA and PSAP are positive in 87% of cases in primary prostatic SRCCs, thus supporting a prostatic origin of the tumor." (PMID 37374005, 2023). "Significantly, the anti-tumor therapeutic strategy of augmenting Tsp-1 expression by the PSAP peptide has also been validated in clinical trials." (PMID 36575174, 2022). "We have previously demonstrated that genetic deletion of Tsp-1, in the entire mouse or specifically in bone marrow-derived cells, abrogates the ability of prosaposin (PSAP) to inhibit tumor growth." (PMID 36575174, 2022). "A glycoproteomic analysis of lung ADC samples and tumor-matched normal tissues has reported the overexpression of PSAP among other glycoproteins in lung ADC." (PMID 36359323, 2022). "In the studies that identified prosaposin as a stimulator of Tsp-1, we also observed the ability of highly metastatic tumor cells to repress Tsp-1 in the TME5." (PMID 36575174, 2022). "Predictably, the median concentration of PSAP in MPM pleural fluid is approximately 4-fold higher than that found in patient sera as consequence of the tight proximity with the tumor." (PMID 36359323, 2022). "Some of the identified proteins have been shown to inhibit apoptosis or cause tumor cells to adapt to hypoxia, thereby promoting tumor cell survival, including clusterin, CD5L, HYOU1, prosaposin, and hepatocyte growth factor activator." (PMID 35659255, 2022). "Once produced by cancer cells, prosaposin acts in a paracrine and endocrine fashion inducing the expression of thrombospondin-1 in stromal cells at primary and distant tumor sites, which blocks neoangiogenesis and delays tumor growth." (PMID 33193295, 2020). "In 38 tumor-specific SE-associated genes, 37 genes showed significantly elevated expression in at least 1 cancer cell line, including DNAJB1, MCU, MPRIP and PSAP." (PMID 29285248, 2017).
tumor (continued). "Additionally, TFPI-2 blocked PSAP-induced enhancement of matrix metalloproteinase-2 (MMP-2) activity, which is closely linked to tumor cell invasive/migratory capabilities." (PMID 40801564, 2025). "This study supports the hypothesis that expression of HOXC11 and the subsequent secretion of PSAP can expedite endocrine resistance to aromatase inhibitor therapy via tumour promotional activation of the AR." (PMID 26341737, 2015). "A stringent cross-comparison identified five proteins (PSAP, MARCKS, eEF1A1, DDX39B, and RACK1) as consistently and differentially regulated across tumor stages." (PMID 42064067, 2026). "Using a GC–SCs co-culture model, we show that SCs enhance PNI potential in GC cells, accompanied by increased expression of prosaposin (PSAP), a lysosomal secretory protein, in both co-cultured cells and PNI-positive tumor specimens." (PMID 41580724, 2026). "Additional immunohistochemical examinations of the resected tumor tissue showed positive expression of AE1/AE3, PSAP, PSMA and partially weakly positive for PSA, as well as nuclear positivity for AR." (PMID 40181402, 2025). "Tissue microarrays and immunohistochemical staining validated strong PSAP positivity in 83% of GBC samples, significantly differing from non-tumor tissues." (PMID 40801564, 2025). "In an orthotopic transplantation model, PSAP knockdown via shRNA led to a notable increase in CD8 + T-cell infiltration, which was followed by a significant reduction in tumor volume compared to the control group, thereby promoting the progression of PDAC." (PMID 40164585, 2025). "In the gene correlation analysis, clustering results for genes such as B4GALNT1, SIGLEC10, and PSAP further support the idea that these genes may participate in similar biological processes or pathways, particularly those related to inflammation, immune regulation, and tumor progression." (PMID 41445741, 2025). "This highlights prosaposin and THBS1 as potential therapeutic targets for inhibiting tumor metastasis." (PMID 39930476, 2025). "In response, MSCs start to secrete the protein prosaposin (PSAP), which promotes tumor growth via activation of the Toll-Like Receptor (TLR)/NF-κB signaling pathway." (PMID 39769286, 2024). "This analysis led to the identification of genes generally associated with cancer cells (MUC1, LGALS3, UGDH, TSTA3, and GALE) or the stromal compartment (LGALS1, PSAP, LGALS9, IDS, and MGAT1) in most of the tumor types analyzed." (PMID 38384845, 2024). "Proteins that have an anti-apoptotic effect on tumor cells or mediate adaptation to hypoxia were detected: clusterin, CD5L, HYOU1, prosaposin, and hepatocyte growth factor activator." (PMID 35659255, 2022). "The expression of PSAP transcript was found significantly downregulated in lung ADC compared to control and the normalized transcript level was lower in this tumor than in MPM." (PMID 36359323, 2022). "Immunohistochemical staining was performed to visualise the expression of BMP1, CD109, LTBP1, PSAP, and NPC2 in human control colonic tissue, primary tumour, and liver metastasis." (PMID 36134447, 2022). "In 41 tumor-specific SEs, several SEs with significant H3K27ac enrichment were close to previously reported tumor-related genes, like MCU, MPRIP and PSAP (Supplementary-2)." (PMID 29285248, 2017). "PSAP promotes invasion via EMT, immune evasion, and tumor microenvironment interactions." (PMID 40361374, 2025). "For example, in response to tumor-secreted prosaposin (PSAP), Gr1+ BMDC secretes TSP-1 at the PMN site, hindering metastasis, and PSAP mimetic peptides could recapitulate this effect." (PMID 37350937, 2023).
tumor (continued). "Neither PSAP nor SULF-1 expression showed a correlation with the tumor stage since the transcript levels were similar in all four stages." (PMID 36359323, 2022). "However, previous studies suggest that several of the identified proteins are potent stimulators of tumor cell proliferation or invasiveness, including SPARCL1, IGF-BP2, osteopontin, FAM3C, TREM2, CD166, prosaposin, and kininogen-1/bradykinin." (PMID 35659255, 2022). "In vivo, shRNA-mediated PSAP knockdown in murine PKCY cells increased intratumoral CD8+ T-cells and reduced tumor volume, suggesting that PSAP may promote the progression of PDAC by inhibiting CD8+ T-cells and PSAP modulation may be a potential new strategy for immunotherapy of PDAC." (PMID 40801564, 2025). "However, knockdown experiments revealed that PSAP depletion did not alter tumor proliferation or migration, ruling it out as a direct therapeutic target." (PMID 40164585, 2025). "The researchers noted that the expression and function of PSAP in STAD may have an important role in facilitating tumor proliferation, tumor formation and metastasis, and may also be a potential biomarker and therapeutic target for clinical treatment and prognostic assessment of GC." (PMID 40801564, 2025). "Studies in tumor microenvironments reveal that TGF-β-induced over-glycosylation of PSAP may impair lysosomal antigen processing, and this observation underscores the intrinsic role of PSAP in maintaining lysosomal integrity and immune signaling." (PMID 40801564, 2025). "Of note, GRN (protein name, progranulin) and PSAP (prosaposin) displayed significant differential abundance between all three clinical timepoints (Pre-OP, Post-OP and REC) and thus are putative candidate biomarkers of GBM tumour burden, tumour recurrence and treatment resistance." (PMID 38212481, 2024). "Several proteins that are involved in tumor growth were present in glioblastoma cyst fluid (for references, see “Discussion” section): SPARCL1, IGF-BP2, osteopontin, FAM3C, TREM2, CD166, and prosaposin promote tumor cell proliferation, migration, and invasiveness." (PMID 35659255, 2022). "The liver metastases and PDX tumor histology slides were negative for AR, PSA, PSAP and ERG protein expression; the tumor strongly expressed KRT7 and focally 34βE12." (PMID 38907236, 2024). "In our case, the tumor cells displayed uniform staining for PSA and PSAP, and they were negative for GATA-3, CDX-2, CK7, and CK20." (PMID 37374005, 2023). "Immunohistochemistry of liver metastatic biopsies and PDX tumor showed lack of expression of typical PCa (e.g., AR, PSA, PSAP, ERG) or neuroendocrine markers (synaptophysin), compatible with double-negative CRPC, but was positive for nuclear β-catenin expression, keratin 7 and 34βE12." (PMID 38907236, 2024). "Among other immunostains not shown, ATRX nuclear expression was retained in all tumor cells, and none of the tumor cells were positive for IDH1 R132H mutant protein, napsin, NKX3.1, CD45, synaptophysin, INSM1, SOX10 protein, p40, CDX2 protein, PSAP, or PSA." (PMID 38845695, 2024).